STAT3 (signal transducer and activator of transcription 3)
Diseases named in the same sentence as STAT3 in open-access papers (continued):
Sharing a sentence is not in itself a finding about the gene and the disease.
Obesity (continued). "A remarkable observation in this context is that TNFR1-mediated activation of JNK, as well as of the oncogenic transcription factor STAT3 and associated IL-6 production promote obesity-related hepatocarcinogenesis, which is also strongly reduced in TNFR1-deficient mice." (PMID 32235829, 2020). "Obesity might cause chronic inflammation via promoting the production of tumor-promoting cytokines such as IL-6 and activation of oncogenes such as STAT3, which has a critical role in regulating cell fate, inflammation, and immunity." (PMID 31988297, 2020). "Thus, EGCG can alleviate the obesity-associated neuroinflammation of the hypothalamus via regulating JAK2/STAT3 signaling pathway." (PMID 31614951, 2019). "However, leptin is unable to exert its effect during diet-induced obesity, and several molecular alterations have been associated with attenuated leptin/STAT3 signaling." (PMID 30441779, 2018). "Moreover, knockout mouse studies have shown that disrupting neural STAT3 causes leptin-resistant conditions such as obesity, diabetes, and thermal dysregulation." (PMID 29596388, 2018). "Hence, cautions should be taken in interpreting our results, and association studies with larger samples in other populations are required to confirm the association between STAT3 SNPs and obesity or hypertriglyceridemia." (PMID 25014397, 2014). "Our observations indicated that common variations of STAT3 could significantly affect the risk of obesity and hypertriglyceridemia in Chinese Han population." (PMID 25014397, 2014). "Extending these observations to other settings of muscle wasting and elevated IL-6 and related cytokines, STAT3 activation might also mediate muscle loss in obesity, advanced age or sarcopenia, inflammatory myopathies, burn, and other diseases." (PMID 21799891, 2011). "Moreover, obesity promotes the formation of a specific NK cell subpopulation through the IL-6/Stat3 signaling pathway, which expresses IL6Ra and Colony Stimulating Factor 1 Receptor (Csf1r), contributing to the onset of obesity, insulin resistance, and associated inflammation." (PMID 40564033, 2025). "Hence, hyperleptinemia and high FFA from increasing the STAT3 phosphorylation in SMCs impairs the leptin signaling pathways during the development of diet-induced obesity, which is associated with disorders of energy homeostasis due to diet-induced obesity." (PMID 36978976, 2023). "Furthermore, Lactucin, a bio-active component found in endive, chicory, and romaine lettuce, has been shown to target pro-inflammatory STAT3 in order to suppress adipogenesis in obesity and obesity-linked complications, whereas NF-κB was blocked by Lactucin in cancer cells." (PMID 35631173, 2022). "In addition, targeting STAT3 can control abnormal metabolic conditions such as diabetes and obesity, which might reduce the risk of cancer associated with those conditions." (PMID 28114390, 2017). "While STAT3 is a well-established role player in multiple types of cancer, recent evidence indicates the importance of STAT3 signaling pathways in obesity-associated cancers and indirectly suggests that diabetes could enhance cancer development via STAT3 activation." (PMID 28114390, 2017). "To investigate whether the polymorphisms of STAT3 confer risks of metabolic disorders in Chinese population, we conducted this association study and found that the common variants of STAT3 were significantly associated with obesity and hypertriglyceridemia in a Chinese Han population." (PMID 25014397, 2014). "Our identification of arcuate POMC neurons of DIO mice as being resistant to STAT3 phosphorylation by leptin at least opens the possibility that those specific cells might play a causal role in the development of hyperphagia and diet-induced obesity." (PMID 22276206, 2012).
Obesity (continued). "Oleoylcarnitine, a metabolite that accumulates following suppression of fatty acid β-oxidation, has been shown to promote hepatocarcinogenesis through STAT3 activation in the context of obesity-driven HCC." (PMID 41184928, 2025). "Constitutive activation of STAT3 enhances brown fat thermogenesis and energy expenditure, as demonstrated by the reversal of obesity in TYK2 knockout mice through increased BAT differentiation." (PMID 40704145, 2025). "Ablating Stat3 in T cells reduces inflammation/obesity-induced insulin resistance, which is in part contributed to by the recruitment of IL-6-producing ATMs in obese mice." (PMID 40801626, 2025). "In this study, we investigated the role of Jak2 and Stat3 in myeloid cells/macrophages in modulating obesity-induced inflammation and insulin resistance." (PMID 40801626, 2025). "Silencing the myeloid cell Stat3 with an in vivo siRNA targeted delivery approach reduces metabolically activated pro-inflammatory ATMs, thereby alleviating obesity-induced insulin resistance." (PMID 40801626, 2025). "Obesity-associated signaling pathways, such as Wnt/β-catenin, PI3K/AKT/mTOR, NOTCH, and JAK/STAT3 signaling pathways, are involved in immunotherapy resistance." (PMID 40863244, 2025). "Using mice with a Jak2 deficiency in the myeloid compartment and Stat3 ablation in myeloid cells, we identify cell-intrinsic Jak2/Stat3 signaling as a critical driver of the pro-inflammatory ATM phenotype in obesity." (PMID 40801626, 2025). "We also demonstrated that Jak/Stat3 in myeloid cells can be targeted for inhibiting obesity/inflammation-induced insulin resistance." (PMID 40801626, 2025). "Our findings suggest that JNK1 functions as a metabolic sensor in adipocytes, activating oxidative metabolism through STAT3 phosphorylation in response to fatty acids, with implications for energy balance and obesity-related metabolic regulation." (PMID 40092442, 2025). "IL-6 plays a dual role: while acutely anti-inflammatory via STAT3, chronic elevation in obesity promotes hepatic acute-phase responses and synergizes with IL-1β to induce β-cell endoplasmic reticulum (ER) stress." (PMID 40699756, 2025). "As FFAs can bind to inflammatory receptors such as TLR4 that drive cytokine production, it is possible that Jak2/Stat3 mediates FA binding to TLR4 to potentiate adipose tissue inflammation during obesity." (PMID 40801626, 2025). "Our previous report demonstrated Stat3 as a target in T cells in reducing obesity-mediated insulin resistance." (PMID 40801626, 2025). "There is strong mechanistic overlap between IL-6 signaling, type 2 diabetes, and obesity, particularly through the activation of STAT3 and AR pathways." (PMID 41139205, 2025). "Our study on Lyz-Cre mice in which Stat3 ablation specifically occurred in the macrophage showed the importance of Stat3 in macrophages in mediating obesity-induced inflammation and insulin resistance." (PMID 40801626, 2025). "Collectively, these data indicate that obesity/FFAs contribute to M1 cytokine expression in macrophages through activating Jak2/Stat3 signaling." (PMID 40801626, 2025). "In obesity, IL-6 elevation initially drives M1-like adipose tissue macrophages (ATMs), contributing to insulin resistance, but sustained IL-6/STAT3 activation favors M2-like phenotypes with immunosuppressive features." (PMID 41310829, 2025). "In mice, adipocyte-derived KYN promotes obesity and insulin resistance by activating the arylhydrocarbon receptor (AhR)/STAT3/IL-6 signaling pathway." (PMID 39125332, 2024). "STAT3 is a transcriptional factor critical to a major signaling pathway generating the anti-obesity effects of leptin." (PMID 39590343, 2024). "Hyperleptinemia has been observed in mice with diet-induced obesity, providing protection through the activation of the STAT3 pathway and beyond, compared to those with mutant LepR obesity." (PMID 38397015, 2024).
Obesity (continued). "STAT3 and SOCS3 play important roles in the downstream pathway of IL-6 and are associated with muscle atrophy in obesity and diabetes." (PMID 38561446, 2024). "Previous studies have shown that Cel reduces the obesity of HFD-fed diabetic obese (db/db) and leptin-deficient (ob/ob) mice by inhibiting endoplasmic reticulum stress and increasing STAT3-dependent leptin signaling." (PMID 38881873, 2024). "Matcha green tea inhibits the JAK2/STAT3 pathway, preventing hypothalamic inflammation induced by obesity." (PMID 39606571, 2024). "As STAT3 has been indicated in both obesity and involution, further exploration of the combined effect of these two independent variables is warranted." (PMID 39525621, 2024). "Mice with a pan-neuronal deletion of signal transducer and activator of transcription 3 (STAT3), the best-known transcriptional effector of leptin action, exhibit profound obesity which is similar to that seen in leptin receptor null mice." (PMID 38821928, 2024). "Both PD-1 ligation and enrichment of leptin in mammary tissues can activate STAT3 signaling in tumor-infiltrating CD8+ T cells, driving increased FAO, which is critical for obesity-associated breast tumor progression." (PMID 39402302, 2024). "Conversely, in obesity tumor models, activated STAT3 promotes FAO while inhibiting glycolysis and IFNγ production in CD8+ effector T cells." (PMID 39402302, 2024). "Studies found that ZRR and its active compounds are bioactive, inducing cancer cell apoptosis by inhibiting STAT3 and NFκB, repressing inflammation by inhibiting NFκB, and fighting obesity by upregulating PPARγ." (PMID 39338294, 2024). "A study employing EGCG in the context of murine diet-induced obesity has reported an increased Treg/Th17 cell balance by decreasing the ratio of STAT3/STAT5 expression." (PMID 38558823, 2024). "Matcha green tea is crucial in preventing obesity-induced hypothalamic inflammation by blocking the JAK2/STAT3 signaling pathway, thereby aiding in the management of obesity-related metabolic syndrome." (PMID 39606571, 2024). "Increased adipocyte leptin secretion in obesity promotes STAT3, CPT1B, and FAO in VAT CD8+ T cells with inhibition of glycolysis." (PMID 39063184, 2024). "Reticuline alleviates airway inflammation in obesity‐related asthma by inactivating the JAK2/STAT3/SOCS3 and p38 MAPK/NF‐κB signaling pathways." (PMID 38286741, 2024). "Intriguingly, overexpression of HDAC5 in the hypothalamus protects mice from diet-induced obesity by enhancing leptin-stimulated STAT3 phosphorylation, which subsequently elevates Pomc expression and inhibits food intake." (PMID 38027481, 2023). "It has also been determined that obesity-promoted HCC development is associated with enhanced production of inflammatory cytokines IL-6 and TNF-α, which is dependent on the activation of signal transducer and activator of transcription 3 (STAT3)." (PMID 36721234, 2023). "SOCS3 is an inhibitor of STAT3, an important marker of leptin signaling as deletion of the STAT3 gene in the CNS induces obesity." (PMID 37571301, 2023). "The signal transducer and activator of transcription 3 (STAT-3) initiate signaling pathways involved in the differentiation of Th17 cells, which are associated with obesity-induced inflammation." (PMID 37334370, 2023). "Surprisingly, we demonstrated that HFD-induced obesity resulted in a significant increase in hippocampal p-STAT3 levels, which was reversed by Zn treatment." (PMID 36977735, 2023). "In the contexts of aging, obesity, stress, infections, injuries and smoking, activation of NF-κB and STAT3 in nonimmune cells triggers a positive feedback loop of the IL-6-STAT3 axis to NF-κB, which is called the IL-6 amplifier." (PMID 37449201, 2023). "Administration of soursop in high‐fat diet‐induced obese rats resulted in a downregulation of the fat mass and obesity‐associated protein (FTO), and an upregulation of the STAT‐3 gene." (PMID 38455221, 2023).
Obesity (continued). "The function of the leptin used was independently validated, given that the same treatment effectively reduced obesity in ob/ob mice and dramatically increased p-STAT3 expression in the Arc." (PMID 37069175, 2023). "In the context of obesity, the hepatic mitochondrial stress-related adaptive functions of STAT-3 signalling appear to be dissociated from the canonical response to cytokine imbalance." (PMID 35887177, 2022). "Trehalose treatment of cells from NGT adults prevented obesity-induced phosphorylation and mitochondrial translocation of STAT3, while lowering inflammatory cytokine production." (PMID 35928250, 2022). "In this study, we assessed if mitochondrial translocation of STAT3 occurred in immune cells in response to obesity and, as an in vivo mimic of obesity sequalae, high fatty acid challenge." (PMID 35928250, 2022). "For example, CREB3, STAT1, and STAT3 are important regulators of glucose and lipid metabolism in models of high-fat diet and obesity." (PMID 36389068, 2022). "Animals with diet-induced obesity have reduced STAT3 phosphorylation in the ARC in response to exogenous leptin administration or inflammatory stimuli and increased basal pSTAT3 in the ARC and VMH." (PMID 35628338, 2022). "In this study, we provide evidence that obesity and fatty acids promote the mitochondrial translocation of STAT3, which exaggerates cellular peroxide generation and inflammation." (PMID 35928250, 2022). "STAT3 upregulation occurs in CD8+ T cells during obesity-associated breast tumor progression, and T cell STAT3 in turn promotes obesity, insulin resistance, and T2D." (PMID 35928250, 2022). "Leptin is the most secreted adipokine in white adipose tissue and it also seems to trigger obesity-related OA via Stat3." (PMID 35548357, 2022). "Fibronectin type III domain-containing protein 5 attenuates cardiac hypertrophy induced by obesity by inactivating JAK2/STAT3-related cardiac inflammation and oxidative stress." (PMID 35812340, 2022). "Collectively, our data show that obesity and fatty acid promote activation and mitochondrial translocation of p-Ser 727 STAT3, resulting in exaggerated peroxide and increased cytokine production." (PMID 35928250, 2022). "Specifically, Kyn stimulates AhR expression to activate the AhR/Stat3/IL-6 signaling in adipocytes, by which it mediates a systemic effect on the development of obesity and insulin resistance." (PMID 35715443, 2022). "In this case, altered IDO1 expression leads to Kyn accumulation, which enhances AhR/STAT3/IL-6 signaling in adipocytes to mediate obesity and insulin resistance." (PMID 35715443, 2022). "Hypothalamic loss of either insulin or leptin receptors leads to hyperphagic obesity in rodents, as does the specific disruption of leptin stimulated STAT3 phosphorylation." (PMID 36111295, 2022). "In correlation with obesity, the modulated leptin signaling was a factor for PC that promoted cell proliferation by activating STAT3 and PI3K/Akt signals." (PMID 37529006, 2022). "Elevated leptin in serum induces activation of Stat3 in cartilage and leads to pathological activation of CD14/TLR4, which further provokes obesity-associated inflammation and MMP-13 expression." (PMID 35548357, 2022). "The up regulation of SOCS3 in POMC neurons leads to the damage of STAT3 signal, resulting in leptin resistance and obesity." (PMID 36615730, 2022). "In mice, a high-fat diet or genetic susceptibility and obesity promoted CRC development by increasing bile acid levels, which led to intestinal barrier impairment and enhanced IL-6/STAT3-related inflammation." (PMID 35154445, 2022). "Rather, T-cell protein tyrosine phosphatase inactivation was found to promote HCC in obesity via STAT-3, independently of T-cell recruitment, NASH, or fibrosis." (PMID 35682957, 2022). "It’s also considered that activation of STAT3 maintained obesity-related metastatic growth of CRC cells." (PMID 36266267, 2022).
Obesity (continued). "On the other hand, OGT activity in liver cells has been linked to insulin and leptin resistance through STAT3 and PTP1B dependent pathways that are known to drive receptor desensitization in the hypothalamus, specifically in response to obesity." (PMID 36111295, 2022). "The increase of SOCS3 expression leads to the down-regulation of JAK2 pathway and the impairment of STAT3 signal, leading to leptin resistance, obesity and abnormal glucose metabolism." (PMID 36615730, 2022). "IL-6 also promoted tumor progression via STAT3 signaling in an obesity-induced liver tumor mouse model." (PMID 35205631, 2022). "We know STAT3 signaling is involved in tumor cell proliferation, survival, infiltration, immunosuppression, obesity, stem cells as well as the pre-metastatic niche." (PMID 34057016, 2021). "This loop of SOCS3 overexpression in obesity and resultant inhibition of STAT3/NFκB activation probably explain the attenuation of VILI observed within the first hours in our diet-induced obese mouse model." (PMID 34489970, 2021). "Mice lacking Stat3 in Lepr-expressing neurons develop hyperphagic obesity supporting the important role of Stat3 signaling in mediating central leptin effects." (PMID 34390703, 2021). "STAT3 is aberrantly activated in a variety of tumors, STAT3 signaling promotes cancer through inflammation, obesity, stem cells and the pre-metastatic niche." (PMID 33413624, 2021). "Production of rIL-22 by engineered Lactobacillus reuteri can also ameliorate hepatic steatosis in mice with diet-induced obesity, as evidenced by reduced triglyceride levels and liver weight via the IL-22/STAT3/Reg3 cascade." (PMID 34944732, 2021). "In summary, the role of HFD-induced obesity on lung tumorigenesis was elucidated both in vivo and in vitro in this study, and highly expressed leptin mediated the activation of STAT3 pathway was likely involved in the mechanism." (PMID 33708630, 2021). "In vitro obesity model showed that STAT3 knockdown significantly attenuated TG content and expression of SREBP1 in LO2 cells." (PMID 34512330, 2021). "In a subsequent study, completely ablating STAT3 from all brain cells in mice was shown to completely recapitulate the obesity, diabetes, infertility, growth retardation, and thermal dysregulation observed in db/db mice." (PMID 34502119, 2021). "Morevover, EPA attenuates obesity-related hepatocellular carcinogenesis development through inhibiting obesity-induced STAT3 activation." (PMID 33801246, 2021). "Accumulating evidence indicates that STAT3 plays a critical role in cancer signaling through inflammation, obesity, stem cells, and the pre-metastatic niche." (PMID 34697301, 2021). "STAT3 is the main signaling factor of IL-6, and obesity has been shown to chronically activate intracellular JAK-STAT3 signaling through increased levels of IL-6 and leptin." (PMID 35087513, 2021). "In the present study, as expected, the increased expression of STAT3 in the obese group promotes obesity through the IL-23/STAT3/Th17 axis." (PMID 34712134, 2021). "GRIM19 attenuated the progression of obesity by regulating STAT3 activity and enhancing brown adipose tissue (BAT) differentiation." (PMID 33467683, 2021). "SOCS3 is upregulated in patients with obesity and impedes the signal transduction of STAT3 via simultaneous binding to JAK and the gp130 cytokine receptor." (PMID 34489970, 2021). "Taken together, these results implied that IL-6 accelerated senescent phenotype of BMSCs through the IL-6/STAT3 pathway, suggesting a potential mechanism for bone loss in HFD-induced obesity." (PMID 33679606, 2020). "On the other hand, we have to realize that STAT3 has many other functions except for disease formation and progression, like cardioprotection, liver protection, and obesity." (PMID 32733808, 2020). "Independent of leptin-deficient obesity and dietary obesity, a course of 8-week IL-4 supplementation improved obesity and impairment in Akt, STAT3, and STAT6 signaling." (PMID 32585823, 2020).